GDF15 (growth differentiation factor 15)
Diseases named in the same sentence as GDF15 in open-access papers (continued):
Sharing a sentence is not in itself a finding about the gene and the disease.
tumor (continued). "We validated differentially expressed proteins at the transcriptional level in clinical tumor specimens, association with patient survival, and absolute concentration to yield three biomarker candidates: MDK, GDF15, and SPINT2." (PMID 38260835, 2023). "In the HCC tumor microenvironment, growth differentiation factor 15 (GDF15) leads to anti-tumor immunosuppression via SLAMF2 expression on regulatory T cells." (PMID 37251372, 2023). "Tumor-derived GDF-15 thus inhibits the LFA-1:ICAM-1 axis in human T cells, thereby interfering with T cell post rolling arrest, firm adhesion to endothelia, crawling and diapedesis across activated blood vessels." (PMID 37474523, 2023). "Neutralization of GDF-15 improves both T cell trafficking and therapy efficiency in murine tumor models." (PMID 37474523, 2023). "Notwithstanding effects on other immune cell subsets, GDF-15 is therefore likely to affect both T cell homing to lymphoid organs and T cell trafficking to tumor tissue." (PMID 37474523, 2023). "From clinical data, we observed that GDF15 levels were positively correlated with invasion depth, nodal involvement, stage, lymphatic invasion, and tumor size." (PMID 36769245, 2023). "This, in turn, stimulates the TAMs to produce growth differentiation factor 15 (GDF15) that contributes to drug resistance by enhancing tumor cell fatty acid β-oxidation." (PMID 37627173, 2023). "In 769-p and Caki-1 cells, GDF15 knockdown significantly promoted tumor viability, proliferation, and migration." (PMID 38082448, 2023). "This concern was assessed in a study in which mice overexpressing human GDF15 using an AAV‐expression system were extensively evaluated for the presence of tumours." (PMID 36992609, 2023). "In line with our results of bioinformatic analyses, GDF15 was downregulated in ccRCC tumor samples at both protein and mRNA level, suggesting a potential anti-tumor role in ccRCC." (PMID 38082448, 2023). "Not only the tumor itself but also adverse effects of chemotherapy have been reported to contribute to increased GDF15." (PMID 37495707, 2023). "In one study, GDF15 overexpression suppressed cell proliferation in vitro and tumor formation in vivo, while in another study overexpression promoted tumor growth in vivo, and proliferation in vitro when stimulated with C5a." (PMID 38260835, 2023). "Analyses from three isotype control-treated mice suggested a correlation between GDF-15 serum levels and tumor size in this model." (PMID 37474523, 2023). "On the other hand, higher expression of BMP4 was observed in locally advanced Luminal B tumours and elevated GDF15 expression in those T3 and T4 tumours, of both Luminal B and TNBC subtypes, with poor OS." (PMID 37333824, 2023). "Using both orthotopic and spontaneous models of PDAC, we observe an upregulation of stromal GDF15 and its newly identified receptor tumor-GFRAL expression, as well as MAGEA expression in Gem treated tumors." (PMID 37814317, 2023). "GDF15 is known to promote immune escape of tumor cells by inhibiting T cell stimulation and cytotoxic T lymphocyte activation." (PMID 36472770, 2023). "Neutralization of GDF-15 enhances T cell infiltration and efficacy of immune checkpoint blockade in murine GDF-15-expressing tumor models." (PMID 37474523, 2023). "Having shown GDF-15 to interfere with immunotherapy in vivo, we explored its potential predictive role for tumor immune escape in humans." (PMID 37474523, 2023). "This suggested that GDF15 production was an important mechanism used by ELFN1-AS1 to modulate CRC tumor cells to avoid NK cell cytotoxicity." (PMID 37147528, 2023). "GDF-15 inhibits the activity of the NF-κB transcription factor, which can be taken to indicate tumor-suppressing properties." (PMID 36230513, 2022). "In contrast, GDF15 knockout in tumor cells inoculated in mice led to decreased proportions of Tregs, reduced tumor growth, and prolonged survival." (PMID 36353620, 2022).
tumor (continued). "Tumor-derived GDF15 was also shown to reduce fat mass by increasing expression of thermogenic genes in BAT and lipolytic genes in WAT and BAT, consistent with higher energy metabolism." (PMID 35646636, 2022). "Results of animal study also showed that GDF-15 was rich in tumor tissues, serum exosomes, and gastrocnemius (GA) muscle tissues of C26 tumor-bearing mice." (PMID 35379793, 2022). "GDF15 polarizes macrophages in the tumor microenvironment into an immunosuppressive state by inhibiting TAK1 signaling to NF-kB and blocking production of TNF and nitric oxide." (PMID 36353620, 2022). "GDF-15 appears to regulate inflammatory pathways in the prostate, with tumor-promoting and/or suppressing functions." (PMID 36230513, 2022). "A rat model of cardiac cachexia shows a protective effect of a neutralizing monoclonal anti-GDF-15 antibody, and an antagonistic monoclonal anti-GFRAL antibody prevents RET activation and subsequent weight loss in tumor-bearing mice." (PMID 36361969, 2022). "We first compared the GDF15 expression levels across different grades in TCGA and found that GDF15 was positively correlated with tumor grades." (PMID 34697897, 2022). "Neutralization of GDF15 was efficacious in mitigating cachexia and improving survival in cachectic tumor models." (PMID 35406637, 2022). "Some evidence indicate that PCa induces osteocytes to secrete GDF15 stimulating tumor growth and invasion and that over-expression of GDF15 leads to increased metastasis of PCa cells." (PMID 35853851, 2022). "We treated U373 cells with rhGDF15 for 2 weeks prior to injecting them into the mouse brains to mimic the secretion of GDF15 from ECs to the tumor microenvironment." (PMID 35280749, 2022). "Considering the effect of tumor purity on microenvironment, we used TIMER algorithm to correct the expression level of key markers of immune cells for tumor purity, and then analyzed their correlation with GDF15." (PMID 34697897, 2022). "In our experimental framework, a group of tumor cells (DTPs) are able to survive a high dose of eribulin by up-regulating the expression of GDF15." (PMID 35626166, 2022). "Studies using transgenic mice expressing GDF-15 showed that GDF-15 exerts both tumor suppressive and progressive activity, suggesting that it has opposite roles during different stages of cancer." (PMID 36008442, 2022). "In our study, cellular response to diltiazem-induced GDF-15 secretion and the anti-tumor effects of GDF-15 were different in strength in different cell lines." (PMID 35963873, 2022). "After adjusted by tumor purity, GDF15 also demonstrated positively correlation to key markers of B cells, T cells, macrophages, monocytes, and neutrophils in LGG, while most of the marker genes of NK cells were negatively correlated." (PMID 34697897, 2022). "GDF15 performs pleiotropic functions in tumor progression, acting either as suppressor or as promoter in early and late stages of tumors, respectively." (PMID 34697897, 2022). "In line with this idea, our analysis also presented aggressive tumor behavior of PTC in patients with high serum GDF15 concentration." (PMID 36046792, 2022). "The influence of changes in GDF-15 expression in C26 or MC38 cells on the potency of tumor cells in inducing muscle atrophy was also observed." (PMID 35379793, 2022). "When GDF15 was depleted in vivo in a pancreatic cancer model with a Ras-driven tumor, immune surveillance was restored and tumor development was delayed, suggesting improved tumor control." (PMID 36353620, 2022). "Remarkably, separate neutralizing antibodies against GDF15 and GFRAL were effective in reversing the weight loss seen in tumor-bearing mice." (PMID 36078078, 2022). "Down‐regulation of GDF15 led to a decrease in the expression of NF‐κB pathway and tumor invasion‐related proteins." (PMID 34697897, 2022). "Even more so, the injection of GDF15-producing tumor cells in mice enhanced adipose and skeletal muscle catabolism." (PMID 36078078, 2022).
tumor (continued). "In comparison, in LNCaP xenografted mouse plasmas, a very high correlation between circulating PSA levels with tumor size (r: 0.94, p = 0.0001), as well as a rather good correlation with GDF-15 were observed (r: 0.82, p = 0.0583)." (PMID 36261691, 2022). "Tumor growth in mice injected with cells expressing GDF15 N70Q mutant was significantly reduced compared to that of mice injected with control 22Rv1 cells." (PMID 35853851, 2022). "Animal study checking the levels of GDF-15 in tumor tissues, serum exosomes, muscle tissues of C26-tumor bearing mice was also conducted." (PMID 35379793, 2022). "Correlations between PSA and GDF-15 concentrations with tumor size at the end of the xenograft experiments were examined to determine which circulating marker most closely varied along with PACE4 inhibitory response." (PMID 36261691, 2022). "GDF-15 also exhibits the heterogenous functions of either tumor-suppressing or tumor-promoting effects." (PMID 35508696, 2022). "GDF15 is regarded as a tumor suppressor gene in the human bladder and the caffeic acid phenethyl ester (CAPE) induces GDF15 expression to inhibit the tumor growth in vitro and in vivo." (PMID 35884930, 2022). "GDF-15 potentially has both protective and tumor-promoting activities, inhibiting tumor growth in the early stages while inversely promoting tumor cell proliferation at later stages via metabolic and immunomodulatory mechanisms." (PMID 36361969, 2022). "The co-presence of PD-L1+ and GDF-15+ excrescences is proposed as a new parameter beyond PSA to define tumor grade progression in prostate biopsies in addition to other common (immuno)histological markers of PCa." (PMID 36230513, 2022). "Although GDF15 is closely related to the immune system and is considered to be the center of inflammation‐induced tissue tolerance, there are few studies on the role of GDF15 in tumor immune regulation." (PMID 34697897, 2022). "Taken together, these findings indicate that silencing GDF15 impairs tumor growth and progression while protecting the bone microenvironment." (PMID 35058441, 2022). "As a result, tumor-protected M2-type TAMs produced growth differentiation factor 15 (GDF15) to enhance the fatty acid β-oxidation in tumor cells, which induced chemoresistance." (PMID 34095111, 2021). "This indicates that depending on the mouse strain, there are different determinants (age/tumor/interdependence) of GDF15 levels." (PMID 35008253, 2021). "In this study, we verified that the expression of GDF15 in HNC tumor tissues and cell lines was elevated, and its overexpression was closely related with the AJCC stage, lymphovascular invasion, and tumor grade." (PMID 34681812, 2021). "Some cellular environmental conditions are able to promote tumor growth via the increased release of GDF15." (PMID 34445593, 2021). "The highlight of our study is the remarkable effect on suppressing tumor growth after combined inhibition of both GDF15 and EGR1, compared to inhibition of EGR1 or GDF15 alone in HNC mouse models." (PMID 34681812, 2021). "We herein aimed to explore the significance of the microRNA (miR)-216a/growth differentiation factor 15 (GDF15) axis in terms of clinical value, tumor immunity, and potential mechanisms in COAD by using multi-omic analysis." (PMID 34948431, 2021). "Among these, JMJD1A was found to regulate a subset of hypoxia-induced genes, ADM, EDN1, HMOX1, and GDF15, and was important for the growth of tumour xenografts in a hypoxic environment." (PMID 34572020, 2021). "Considerably higher expression of GDF15 protein was detected in all of four tumor samples relative to the normal tissues." (PMID 34681812, 2021). "The results of TISIDB demonstrated that GDF15 negatively correlated with a majority of the immunoinhibitory genes in COAD tumor tissues." (PMID 34948431, 2021). "The Cancer Genome Atlas (TCGA) data show that the expression of GDF15 is significantly associated with tumor AJCC stage, lymph vascular invasion and tumor grade in HNC." (PMID 34681812, 2021).
tumor (continued). "Accordingly, single-cell RNA sequencing of tumor and non-tumor tissues from HCC patients revealed that HSCs from tumoral areas showed a significant increase in GDF15 expression, suggesting the key role of this protein in tumor progression." (PMID 35008212, 2021). "The purpose of this study was to explore the significance of the miR-216a/GDF15 axis in terms of clinical value, tumor immunity, and potential mechanisms in COAD." (PMID 34948431, 2021). "WFDC2 was best at predicting respiratory system-related deaths, while GDF15 was best at predicting neoplasm and other deaths." (PMID 34145379, 2021). "The mitochondrial dysfunction and retrograde mitochondrial signaling evidentially produced overexpression of fibroblast growth factor 21 (fgf21) and growth differentiation factor 15 (gdf15) in tumor patients." (PMID 34717757, 2021). "Result shows that the level of GDF15 in tumor tissue tends to be higher than that of normal tissue, although it is not statistically significant (data not shown)." (PMID 34681812, 2021). "Activated HSCs accelerate tumor growth and progression by releasing GDF15 in an autophagy-dependent manner." (PMID 34440674, 2021). "The authors validated the effects of tumour cells on LX-2 activation and GDF15 expression in a xenograft in vivo study and validated in 12 HCC patients that tumour-associated HSCs express higher levels of GDF15 than non-tumour HSCs." (PMID 34885024, 2021). "The remaining 16 genes were highly expressed in tumor tissues of LUAD patients, and most of them (14/16) were identified as risk factors for LUAD patients, except for DPP4 and GDF15." (PMID 34307361, 2021). "Some theses indicated that GDF15 had tumor suppressor activity, while other data manifested that it had oncogenic activity." (PMID 34681812, 2021). "Previous research reported that GDF15 can enhance the phagocytosis of dendritic cells in tumor environment." (PMID 34566964, 2021). "For example, elevated GDF15 levels as a poor prognostic marker and tumor promoter have been noted, whereas its tumor-suppressive role has also been revealed." (PMID 34948431, 2021). "GDF‐15 expression showed a pattern in which the highest mean levels were observed in the normal prostatic glands adjacent to tumor." (PMID 33784024, 2021). "GDF15 is overexpressed in tumor tissues of HCC patients, and its expression is positively correlated with HCC progression." (PMID 34440674, 2021). "Specifically, in a cell culture system resembling a tumor microenvironment, activated HSCs (aHSCs) showed upregulated levels of growth differentiation factor 15 (GDF15) compared to the inhibited autophagy condition." (PMID 35008212, 2021). "To gain molecular insights into the role of GDF15 in COAD, we further used UALCAN analysis to acquire 22 genes positively correlated with GDF15 in COAD tumor tissue." (PMID 34948431, 2021). "Further analysis indicated GDF15 is a component of multiple downregulated tumor-promoting gene sets." (PMID 33850096, 2021). "GDF-15 was further identified in an unbiased screening for tumor-derived factors that suppress dendritic cell function." (PMID 32508832, 2020). "Further, depletion of CD8 T cells in tumor bearing mice abolished the GDF15 induced protection from tumor growth." (PMID 32502202, 2020). "Of note, GDF-15's potential role in the exclusion of T cells from the tumor microenvironment would be consistent with its preferential expression in solid tumors as opposed to hematological malignancies." (PMID 32508832, 2020). "Quantification of the tumor and stromal compartments demonstrated that the percentage of the stromal cell component of the tumors was lower in GDF15-KD tumors than in control tumors in both the PBS- and cisplatin-treated groups." (PMID 33086658, 2020). "The histological and RNAseq studies of the GDF15-knocked down, A2780 cell line-induced tumor revealed that the ratio and canonical pathways of stromal/tumor were modified by secretory GDF15." (PMID 33086658, 2020).
tumor (continued). "The phenotypic changes in CD8 T cells we have identified are also consistent with GDF15 stimulation of tumor immunity." (PMID 32502202, 2020). "To further elucidate the role of GDF15 in tumor progression in vivo, we generated HT29 cells with stably expressing shGDF15 to abrogate endogenous GDF15 in cells." (PMID 32076610, 2020). "Reported tumor suppressor functions of GDF-15 mostly occur during the early phases of tumor development and appear to be restricted to the primary tumor." (PMID 32508832, 2020). "GDF15 is highly expressed in multiple disease states, such as organ injury, hypoxia, pressure and tumor, and it promotes cell apoptosis and inhibits tumor growth." (PMID 33098235, 2020). "Infusion of GDF15 into mice bearing orthotopic TRAMP tumor, substantially reduced tumor growth that was further reduced by concurrent PD1 antibody administration." (PMID 32502202, 2020). "Our mouse models allowed us to detect GDF15 secretion into the blood and the impact of GDF15 level on the tumor and stroma interaction in vivo." (PMID 33086658, 2020). "Our earlier data suggested that GDF15 mediated protection from tumor growth required intact adaptive immunity and CD8 T cells." (PMID 32502202, 2020). "For this reason, whilst adaptive immunity has no visible impact on the growth of tumors growing spontaneously in TRAMP mice it has a major impact on TRAMPrag-/- tumor cells and that impact is even greater in GDF15 overexpressing transgenic MIC-1fms mice." (PMID 32502202, 2020). "GDF15 overexpression or recombinant protein protects from TRAMP tumor growth by modulating CD8 T cell mediated antitumor immunity and augments the positive effects of anti-PD1 blockers." (PMID 32502202, 2020). "Visfatin induces growth differentiation factor 15 (GDF15)/Akt axis to elevate the progression and proliferation of tumor cells." (PMID 32503307, 2020). "The improved survival and reduced tumor size that is seen in GDF15 overexpressing TRAMPfmsmic mice is completely abrogated in triple transgenic TRAMPfmsmic/rag-/- mice, that also lack adaptive immunity because of deletion of the Rag1 gene." (PMID 32502202, 2020). "GDF-15 also remains highly predictive regarding clinical outcome in multi-variate analyses with other markers reflecting tumor burden." (PMID 32508832, 2020). "GDF15 was discharged into exosomes by drug-resistant cells after 5-FU chemotherapy, which subsequently regulated the tumor microenvironment through mechanisms such as angiogenesis." (PMID 33193874, 2020). "A study suggests that the TGF-β/BMP family member GDF15, secreted by CAFs, exerts not only a paracrine effect on tumor growth, migration, and invasion, but also has tumor-instigating properties on distant PCa cells." (PMID 32668821, 2020). "More importantly, we proved that GDF15 expression impacts ovarian tumorigenesis by modulating the canonical pathways in both the tumor cell and stroma cell components of the tumor." (PMID 33086658, 2020). "GDF15-KD A2780 cells formed larger tumors in nude mice than did GDF15-NT A2780 control cells, suggesting that basal level of GDF15 affects tumor growth." (PMID 33086658, 2020). "Previous studies have shown that GDF15 expression is elevated in certain human tumors, and dysregulation of GDF15 has been correlated with tumor progression and poor clinical outcomes." (PMID 33123476, 2020).